BMP2 (bone morphogenetic protein 2)
Diseases named in the same sentence as BMP2 in open-access papers (continued):
Sharing a sentence is not in itself a finding about the gene and the disease.
lung carcinoma (continued). "BMP2 was detected in the medium when lung cancer cell lines were cultured in either SFM or DMEM with 5% FCS." (PMID 23593444, 2013). "Although recombinant BMP2 proteins induce a transient increase in the expression of Id1 in lung cancer cells, the role of the BMP signaling cascade in regulating the basal expression levels of the Id family members in cancer cells has not been elucidated." (PMID 23593444, 2013). "Ectopic expression of BMP-2 in A549 lung cancer cells greatly enhanced metastatic growth in a murine model of lung cancer following tail vein injection." (PMID 23593444, 2013). "Prior studies have shown that lung cancer cell lines produce the mature BMP2 protein, which is the active form." (PMID 23593444, 2013). "The BMP2 antagonist, noggin, reduces mixed metastatic lung cancer lesions in bone and the growth of transformed lung cells in monolayer and in soft agar." (PMID 21508438, 2011). "This is particularly relevant to lung cancer, because BMP2 RNA and protein levels are abnormally elevated in lung tumors." (PMID 21508438, 2011). "Conversely, other research has suggested that BMP-2 can stimulate the growth of tumor cells in vitro, such as lung cancer and prostatic carcinoma." (PMID 20587070, 2010). "High BMP2 expression is a promising therapeutic target in lung cancer." (PMID 38627856, 2024). "Finally, BMP2 expression is correlated with metastatic burden and STK11 loss in lung cancer and mediates activation of SMAD transcription factors, which are known YAP1 binding partners." (PMID 37968341, 2024). "Additionally, using an in vivo orthotopic mouse model, we demonstrated that the BMP2-depleted lung cancer cells are less metastatic than BMP2-proficient control cells." (PMID 36175474, 2022). "Furthermore, mycoplasma infection induces transformation and tumorigenicity in the normal human lung cell line, BEAS-2B, and promotes lung cancer angiogenesis by elevating bone morphogenetic protein 2 (BMP2) levels." (PMID 35642013, 2022). "Silencing the expression of BMP-2 inhibits lung cancer cell proliferation and migration." (PMID 34307117, 2021). "BMP2 could induce lung cancer migration, invasion, and EMT via activation of MAPK/Runx2/Snail signaling pathway." (PMID 32195173, 2020). "At the early stage, BMP2 enhances lung cancer cells to migrate and invade to the bone tissues." (PMID 32750747, 2020). "It was reported that BMP2 induces the phosphorylation of mTOR and p70S6 kinase in lung cancer cell lines through a Smad 1/5–independent mechanism and promotes motility and invasion of chondrosarcoma cells, gastric cancer cells and pancreatic cancer cells by activating PI3K/Akt signaling pathway." (PMID 28455969, 2017). "Further in vitro evidence suggests an essential role of BMP2 in lung cancer." (PMID 25924783, 2015). "In human lung cancer, BMP2 has been shown to be over-expressed." (PMID 25924783, 2015). "In line with our findings, BMP2 has been shown to be over-expressed in lung cancer." (PMID 25924783, 2015). "In summary, our data show that BMP-2 silencing in the lung cancer cell lines A549 and H460 suppressed their proliferation and migration, thereby suggesting that BMP-2 might be a novel therapeutic strategy for human NSCLC." (PMID 24946687, 2014). "BMP-2 is aberrantly expressed in approximately 98% of lung carcinomas." (PMID 24946687, 2014). "In addition, forced expression of BMP-2 in NSCLC cell lines significantly enhanced tumor growth in a mouse model of lung cancer following tail intravenous injection of tumor cells." (PMID 24603907, 2014). "Finally, BMP-2 is overexpressed in the majority of lung carcinomas and stimulates the growth and progression of lung tumors." (PMID 24946687, 2014). "Inhibition of KDM4C with shRNAs or SD70 treatment reduced the basal expression levels of TGF-β2, BMP2 and JUND while increasing the expression level of GDF11 in lung cancer cells." (PMID 33558705, 2021).
lung carcinoma (continued). "The expression levels of VEGF, BMP2, and BMP4 mRNA were significantly higher (7.1-fold, 25.6-fold, and 2.3-fold, respectively) in lung cancer samples than those in adjacent normal lung tissues." (PMID 34722241, 2021). "Bone morphogenetic protein 2 (BMP-2) is a member of the TGF-β superfamily that is closely correlated with many malignancies, particularly lung cancer." (PMID 24946687, 2014). "For example, Bone morphogenetic protein-2 (BMP2) is overexpressed in the majority of human lung carcinomas independent of cell types." (PMID 33005178, 2020). "Different from BMP2, BMP6 has been reported to be a tumour suppressor in lung cancer, which may be epigenetically silenced in lung cancer." (PMID 32750747, 2020). "Targets of BMP2 were among the most enriched gene sets in breast but not lung cancer, which is intriguing given the role of this gene specifically in breast CSCs." (PMID 25793737, 2015). "To test whether metastatic cancers express higher BMP2 levels than non-metastatic cancers, we collected lung cancer tissue from National Cheng Kung University Hospital (NCKUH, Taiwan) and separated the samples into two groups." (PMID 36175474, 2022). "Unlike BMP2, insulin activated Akt in lung cancer cells during starvation." (PMID 35641992, 2022). "Thus far, no retrospective research has directly analyzed the role of BMP2 in lung cancer bone metastasis." (PMID 34722241, 2021). "However, the effects of silencing BMP-2 on lung cancer cell proliferation and migration were not clear." (PMID 24946687, 2014). "However, the effects of silenced BMP-2 on lung cancer cell proliferation and migration are not clear." (PMID 24946687, 2014). "For example, overexpression of BMP-2 is associated with ∼98% of NSCLC, but little or no activity of the BMP signaling cascade are detected in adult normal lung tissues, suggesting that blocking BMP signaling pathway may be an effective approach for lung cancer treatment." (PMID 24603907, 2014). "Finally, we identified BMP5 as having significantly differential expression and superior prognostic value, rather than BMP2, BMP4, and BMP7, which have been extensively explored in lung cancer." (PMID 34745928, 2021). "In addition, although CAV1, SMAD7, BMP2, EDN1, and CXCL12 were not significantly different in the prognostic analysis in our study, they also play important roles in the occurrence and development of lung cancer." (PMID 34820377, 2021).
prostate carcinoma (32 papers, 2010 to 2025). A carcinoma that arises from epithelial cells of the prostate gland. "It has been previously investigated in epithelium of the human colon where inactivation of BMP2 was shown to be associated with aggressive course of prostatic cancer." (PMID 32423112, 2020). "One neutral single nucleotide polymorphism p.S38S (score 0.15) was found in BMP2 and one pathogenic mutations causing prostate cancer, p.T214T was identified in BMP4." (PMID 29719616, 2018). "We identified one pathogenic mutation, p.T214T in BMP4, causing prostate cancer and one neutral mutation p.S38S in BMP2." (PMID 29719616, 2018). "In fact, low levels of BMP-2 have been implicated in poor patient prognosis in prostate cancer." (PMID 32933207, 2020). "Finally, several studies suggest that BMP2 promotes progression and induces biochemical recurrence in prostate cancer, which is consistent with the positive association found here between BMP2 and risk score." (PMID 33197890, 2020). "On the other hand, BMP2 expression is decreased in prostate cancer compared to benign prostate tissue, and BMP receptor expression is often lost during tumor progression." (PMID 36054271, 2023). "A recent study on colorectal cancer demonstrated the role of BMP2 in reducing growth, enhancing apoptosis, and decreasing the development of tumors in vivo, supporting that the decreased expression of BMP2 also leads to the progression of prostate cancer." (PMID 35800452, 2022). "In prostate cancer bone metastasis, cancer cells release BMP2 via microvesicles to promote pre‐osteoblasts differentiation." (PMID 32750747, 2020). "In this study, we constructed a model using a Cox proportional hazards model based on the expression of eight immune-related genes that were associated with prognosis in prostate cancer: EDNRB, ANGPTL2, TNFSF15, TNFRSF10D, EDN2, BMP2, NLRP14, and PLK1." (PMID 33197890, 2020). "From July 2007 to August 2010, radical prostatectomy specimens from 90 patients with clinically localized prostate cancer (mean age, 62.7 years, mean follow-up 90.4 months) were assessed for BMP-2 expression using immunohistochemistry." (PMID 30013089, 2018). "We evaluated the prognostic value of BMP-2 expression in prostate cancer tissue via immunohistochemistry in prostate cancer patients." (PMID 30013089, 2018). "BMP2 is over-expressed in many different tumor types, notably carcinomas of the prostate, lung, colon, breast, and ovary, where it is known to promote cellular motility, invasion and metastases." (PMID 27494873, 2016). "However, in vitro, BMP2 was found to enhance C4‐2B prostate cancer cell invasiveness and mediate TNF‐α‐induced invasion." (PMID 36054271, 2023). "BMP2 had also been reported to play roles in the migration of prostate cancer cells in vitro." (PMID 32195173, 2020). "BMP2 has been specifically associated with the migratory and invasive capacity of prostate and liver cancer cells in vitro, while the BMP antagonist, Noggin, inhibits the migration of BMP2-stimulated prostate cancer cells." (PMID 32708289, 2020). "Therefore, decreased BMP-2 expression in prostate cancer tissue was correlated with the prognostic factors for BCR-free survival in patients with prostate cancer." (PMID 30013089, 2018). "Furthermore, BMP-2 enhances the phosphorylation of IκBα and the nuclear translocation of NF-κB in gastric and prostate cancer cells." (PMID 27661009, 2016). "In this regard, it is possible that WISP1’s positive influence on BMP-2 could be one way it increases migration, invasion and spread of prostate cancer to bone." (PMID 23977121, 2013). "Since the role of BMPs in the formation of prostate cancer metastases remains unknown and controversial, we tested whether BMP-2 could influence PC cell growth, migration and invasion." (PMID 20537156, 2010).
prostate carcinoma (continued). "In long-term experiments, prostate cancer cells exposed to BMP-2 concentrations attainable in vitro (50-100 ng/ml) from endothelial cells exposed to 5 μM 4HPR, showed a slight but significant decreased proliferation and reduced chemotactic and invasive activities." (PMID 20537156, 2010). "PI3K/Akt-NF-kappaB signaling may promote prostate cancer (PC) bone metastasis in part by regulating transcription and activation of BMP2 and subsequent phosphorylation of Smad1/5/8 which are critical downstream targets of BMP2 signaling." (PMID 25938545, 2015). "Because BMPs have very important roles in the development of bone metastasis in prostate cancer cells, it might be possible that BMP-2 in the bone environment promotes metastasis of cancer cells to bone through upregulation of the intrinsic expression of Id-1 in cancer cells." (PMID 20010941, 2010). "In addition, we found that BMP-2, a 4HPR target with antiangiogenic activity, decreased prostate cancer cell proliferation, migration and invasion by down-regulating the pathway described involving AKT phosphorylation, β-catenin stability and cyclin D1 expression." (PMID 20537156, 2010). "Osteoblast-secreted BMP2, in turn, was found to activate the AKT/NFKB axis in prostate cancer cells, leading to enhanced migration of the cells via an activation of the transmembrane adhesion receptors integrin β1 and β3." (PMID 34064589, 2021). "It was also observed 1,25(OH)2D3 or vitamin D analog regulated mRNA expression of several BMP forms i.e., BMP6 in primary prostate cancer cells, BMP2 and BMP6 in MCF10AT1 cells, and TGFβ1 and BMP2A in squamous cell carcinoma lines." (PMID 34208589, 2021). "In human prostate cancer cells, this metal complex disrupted the LSD1-H3K4me2 interaction and enhanced the amplification of p21, FOXA2, and BMP2 gene promoters." (PMID 31801559, 2019). "By increasing the expression of OPG and BMP-2, GB4-BPL@siCXCR2/pPTEN could enhance the ability of Enz to inhibit bone resorption, promote bone formation, reduce tibial osteolytic lesions in prostate cancer and enhance bone protection." (PMID 40860155, 2025). "The LNCaP human prostate cancer cell line exhibits increased proliferation upon BMP-2 treatment in the absence of androgen, however when treated with androgen, BMP-2 inhibited cell growth." (PMID 32318332, 2020). "Similarly, BMP-2 and BMP-7 were reported to promote the characteristic morphologic conversion of EMT in gastric and prostate cancer cells." (PMID 27661009, 2016). "It is possible the coupled interference of TGF-β1 and BMP-2 by anti-WISP1 treatment could in turn alter the composition of the extracellular matrix (ECM), now known to be affected by and influential to prostate cancer cell behavior." (PMID 23977121, 2013). "In order to test whether our identified BMPR1A-biased BMP2 expression biomarker was useful across tumour types, we investigated disease free survival in Ovarian, Lung, Pancreatic and Prostate cancers, but found no significant alterations." (PMID 27114889, 2016). "We found that BMP-2 modulates AKT phosphorylation, but not that of pGSK3β (data not shown), further confirming that in prostate cancer cells β-catenin nuclear signaling is mainly controlled by AKT activity." (PMID 20537156, 2010).
colon cancer (30 papers, 2009 to 2025). "The SMAD7, SMAD3, BMP2, and C-MYC regions were associated with colon cancer; however, after BH correction, only SMAD7 (PBH = 0.04) and SMAD3 (PBH = 0.009) remained statistically significant." (PMID 31434255, 2019). "BMP2 has recently been described to contribute to the promotion and development of colon cancer stem cells, together with an increase in drug resistance." (PMID 31450563, 2019). "Although BMP-2 inhibits the proliferation of many cancer cells including breast, gastric, and colon cancer cells, the specific mechanisms of rhBMP-2 in esophageal squamous cancer cell death in vitro or in vivo have never been clearly elucidated." (PMID 27230238, 2016). "We previously reported, in a study with a larger sample size, that rs3178250 (BMP2) was associated with increased risk (ORTC/CC 1.20 95 % CI 1.05, 1.38) of developing colon cancer, as well as rectal cancer (ORCC 1.63 95 % CI 1.02, 2.60)." (PMID 27107574, 2016). "Overexpression of BMP-2 has been found to decrease cell proliferation, migration, and invasiveness of human colon cancer cell lines." (PMID 25797254, 2015). "In the present study, we investigated the effect of BMP2 on the proliferation, migration, invasiveness and tumor growth capabilities of human colon cancer cells." (PMID 24993644, 2014). "We only observed marginally significant associations with BMP2 (PARTP = 0.083), BMPR1A (PARTP = 0.053), BMPR1B (PARTP = 0.069) for colon cancer survival." (PMID 25541970, 2014). "BMP2 was shown to suppress colon cancer cell migration and invasiveness as assessed by cell wound healing assay and Boyden chamber Transwell assay." (PMID 24993644, 2014). "To achieve high levels of exogenous BMP2 expression, we constructed an adenovirus vector that overexpresses BMP2 and also generated the piggyBac transposon-mediated stable BMP2 overexpression cell line using the commonly used human colon cancer line HCT116." (PMID 24993644, 2014). "Colon cancer cultures, however, co-cultured with bacteria containing the BMP-2 gene exhibited significant caspase-3 activity, testimony of a potent anticancer activity." (PMID 22315590, 2012). "Demonstration of efficacy on colon cancer cells of bacterially produced BMP-2 would constitute an important step forward to come to applying transgenic bacteria for cancer prevention." (PMID 22315590, 2012). "In addition, SLC7A8 was upregulated alongside two tumour suppressor genes, CEACAM1 and BMP2, in human colon cancer cells after exposure to anti-tumour agent." (PMID 32200487, 2020). "Additional genetic variants retaining significance by PACT were rs6983267 in C-MYC previously identified in a meta-GWAS, rs235770 in BMP2 previously associated with colon cancer risk, and a novel association of rs4645887 in BAX." (PMID 31027226, 2019). "However, we recently reported that TrkC blocks bone morphogenetic protein 2 (BMP2)-mediated tumor suppressor activity in colon cancer." (PMID 28455963, 2017). "BMP-2 enhanced the motility and invasiveness of colon cancer cells by inducing CSC proliferation." (PMID 27661009, 2016). "To determine whether Dragon's action on colon cancer requires BMP2 and BMP4, we first examined BMP2 and BMP4 expression in CT26.WT and CMT93 cells." (PMID 26029998, 2015). "BMP2 was shown to suppress colon cancer cell migration and invasiveness." (PMID 24993644, 2014). "Furthermore, we report a potential approach for inducing colon cancer cells death by apoptosis mediated by the recombinant BMP-2 protein produced by this E. coli." (PMID 22315590, 2012). "Besides, BMPs as part of TGF-β superfamily, might be also involved in this process as statins were reported to activate BMP2 expression to induce colon cancer cell apoptosis." (PMID 34621019, 2021). "Activation of BMP2/4 signaling could inhibit the self-renewal but enhanced the differentiation of cancer stem cells in colon cancer and further promoted the sensitivity of colon cancer cells to chemotherapy." (PMID 32195173, 2020).
colon cancer (continued). "Thus, our results strongly suggest that BMP2 may play an important inhibitory role in controlling the proliferation and aggressive features of colon cancer cells." (PMID 24993644, 2014). "Oleic acid, linoleic acid and palmitic acid have been shown to modulate BMP-2, beta-catenin, LGR-5, Jagged 1, Ki-67 expression; affects Wnt, Notch and BMP signaling pathways in colon cancer." (PMID 41346617, 2025). "In contrast, the positive role of BMP2 in CSC regulation was observed in glioblastoma and colon cancer." (PMID 34277708, 2021). "It has also been reported that bone morphogenetic protein-2 (BMP-2) signalling activates STAT3 and promotes EMT and colon cancer stemness in CRC, which contribute to drug resistance." (PMID 34733591, 2021). "For this reason, we performed in vitro studies in colon cancer cells (SW-620) treated with RE to confirm and validate the specific effect of RE on decreasing the expression levels of JAK1, NFE2L2, CHKA, and BMP2 genes." (PMID 31450563, 2019). "We also observed the upregulation of Bmp2 and Tgfbr2 by MOB1A/B knockdown in the Caco-2 colon cancer cell line." (PMID 30349003, 2018). "BMP-2 induces EMT and promotes colon cancer cell migration and invasion by increasing STAT3-mediated tumor stemness." (PMID 27661009, 2016). "Meanwhile, BMP2 was shown to be hypermethylated in CRC and has been observed to induce epithelial–mesenchymal transition, thereby potentiating the metastatic capabilities of colon cancer cells." (PMID 37628872, 2023). "In colon cancer, knockdown of STAT3 reversed BMP2-induced CSC formation." (PMID 34277708, 2021). "Evidently, however, mucosal delivery of the colonic tumour suppressor BMP-2 could prove highly interesting in this respect, but would require proof that BMP produced in the bacterial context is capable of counteracting colon cancer cells." (PMID 22315590, 2012). "For rs3178250 (BMP2) (ORTC/CC = 1.18, 95 % CI 0.99–1.40) we observed that the heterozygote genotype (relative to homozygous normal) was associated with ~25 % elevated colon cancer risk, while the rare homozygous variant genotype was (non-significantly) associated with reduced risk." (PMID 27107574, 2016).